INS (insulin)
Diseases named in the same sentence as INS in open-access papers (continued):
Sharing a sentence is not in itself a finding about the gene and the disease.
Insulin resistance (continued). "Tumor necrosis factor and free fatty acids are involved in the development of insulin resistance, and then the activation of PPARγ contributed toward down-regulation of both parameter and increased the insulin sensitivity." (PMID 32815547, 2020). "A substantial body of evidence has implicated ceramides, a sphingolipid intermediate, as potent antagonists of insulin action that drive insulin resistance." (PMID 32098447, 2020). "It has been established that dysfunction and negative regulation of the insulin-mediated signaling pathway can affect insulin activity, resulting in insulin resistance." (PMID 33133211, 2020). "Alternatively, CB overactivation can impact on insulin secretion and insulin resistance indirectly, by inducing tonic sympatho-excitation." (PMID 32698380, 2020). "The insulin resistance induced by HFD feeding stimulates the secretion of higher levels of insulin in an effort to compensate for the lower response of target tissues to the hormone." (PMID 32183232, 2020). "The main pathological basis of T2DM is insulin resistance (IR) and relatively insufficient insulin secretion." (PMID 33381036, 2020). "Limitations of this study include the small sample size of this pilot trial and the heterogeneous study population, and inclusion of participants with only mild insulin resistance, perhaps hampering our ability to detect improvements in insulin sensitivity." (PMID 32150549, 2020). "Subsequently, the expression levels of key proteins in the insulin signaling cascade were investigated in order to assess the influence of miR-802’s up-regulation of hepatic insulin resistance." (PMID 32545342, 2020). "Obese, insulin resistant individuals, and elderly people (with insulin resistance) have been found to have lower levels of HSP70." (PMID 32690985, 2020). "Systemic insulin resistance is preceded by the development of insulin resistance in key insulin target tissues, such as skeletal muscle and white adipose tissue (WAT)." (PMID 32041341, 2020). "The insulin levels of CP-treated db/db mice were significantly decreased and the surrogate biomarker for insulin resistance, HOMA-IR, was consistently reduced." (PMID 33255372, 2020). "Such compensatory increase in insulin levels are often observed in patients with metabolic diseases; however, if unchecked will ultimately progress to worsening insulin resistance and lead to pancreatic failure." (PMID 32101528, 2020). "A prolonged high blood level of insulin, attributed to hepatic insulin resistance, contributes in the progression of NAFLD to liver fibrosis, NASH and possibly hepatocellular carcinoma." (PMID 32792584, 2020). "It has been verified that DHY can improve glucose metabolism and insulin sensitivity and ameliorate insulin resistance not only in experimental studies but also in terms of clinical efficacy." (PMID 32933152, 2020). "Macrophage-derived pro-inflammatory signalling molecules also play important roles in the induction of insulin resistance in peripheral insulin sensitive cells." (PMID 33396555, 2020). "As insulin resistance and insulin secretion defects contribute to both GDM and T2DM, the changes after delivery in the short term and long term are necessary to explain the transition from GDM to T2DM." (PMID 32184821, 2020). "KKAy mice are characterized by insulin resistance with increased blood glucose, circulating insulin levels and increased lipogenesis in the liver and in adipose tissue." (PMID 33324348, 2020). "Type 2 diabetes mellitus (T2DM) is a metabolic disorder characterized by chronic hyperglycemia, increased insulin resistance over time, and progressive failure of pancreatic insulin secretion." (PMID 32372981, 2020). "The subsequent increase in the quantity of β-cells further enhanced insulin-secretion capacity sufficiently to overcome peripheral insulin resistance." (PMID 32595604, 2020).
Insulin resistance (continued). "Consistent with these adipokine effects contributing to insulin resistance (IR), serum insulin levels were substantially elevated in HCD-fed mice." (PMID 32163524, 2020). "Both blood insulin measurement and the insulin resistance approximation using HOMA-IR showed that HFD feeding caused alterations in glucose homeostasis." (PMID 32151028, 2020). "Insulin resistance, as defined by the American Diabetes Association (ADA), is a condition in which the response of cells to insulin is impaired with respect to carbohydrates, lipids, and proteins, resulting in elevated blood glucose levels." (PMID 32375231, 2020). "First, the glycemic effect of beverages on insulin demand can result in glucose intolerance and insulin resistance." (PMID 33218344, 2020). "By contrast, MFN2 overexpression ameliorated HFD-induced insulin resistance by targeting insulin signaling pathways." (PMID 32630236, 2020). "Increased insulin resistance due to obesity, inflammation, aging, oxidative stress, and decreased physical activity elevate insulin secretion, to overcome insulin resistance and maintain normoglycemia." (PMID 32161549, 2020). "A further role has been identified in insulin resistance through targeting of the insulin-like growth factor 2 receptor and subsequent activation of the insulin signaling pathway." (PMID 31979312, 2020). "Treatment of diabetic rats with the DBT34 microbial extract or sitagliptin mitigated the alterations in insulin resistance, β-cell function, and insulin sensitivity by reducing glucose and insulin levels." (PMID 33036127, 2020). "There were no clear associations between SLI in childhood and other cardiovascular risk factors, including adiposity, total and LDL cholesterol, triglycerides, glucose, insulin and insulin resistance." (PMID 32507748, 2020). "T2D and obesity have been reported to be the metabolic diseases that are characterized by impaired insulin action and insulin resistance induced by low-grade inflammatory." (PMID 32382544, 2020). "After 16 weeks, serum insulin levels and the homeostasis model assessment of insulin resistance (HOMA-IR) index in the SQE group were significantly lower compared with the HF group." (PMID 33297496, 2020). "Next, to examine the effects of BAFF depletion on aging-induced insulin resistance, we compared glucose tolerance and insulin sensitivity between aged BAFF−/− and WT mice." (PMID 32698539, 2020). "While insulin resistance decreases during normal pregnancy, insulin-stimulated glucose uptake is reported to drop by an extra 54% in GDM patients compared with normal pregnant controls, leading to hyperglycemia." (PMID 32252821, 2020). "As lipids accumulate, the levels of the CER and DAG increase, which impairs the insulin signaling pathway and promotes insulin resistance." (PMID 32082422, 2020). "The insulin‐glucose parameters indicated that the PCOS patients had insulin resistance in the present study." (PMID 32869942, 2020). "In this part, we will mainly focus on the role of the PPP in obesity-related insulin resistance, insulin secretion and chronic diabetic complications." (PMID 32582032, 2020). "Insulin resistance (IR) is a decreased tissue response to insulin-mediated cellular actions, with a decreased ability of insulin to stimulate the use of glucose and suppress hepatic glucose and output." (PMID 32481506, 2020). "These extracts were found to effectively ameliorate insulin resistance condition, increase insulin sensitivity, decrease body weight gain and lipids accumulation." (PMID 32825758, 2020). "In obesity, macrophages and other immune cells accumulate in organs affected by insulin, leading to chronic inflammation and insulin resistance." (PMID 33551809, 2020). "Glucose, insulin, leptin, and visfatin levels in sera, as well as the homeostatic model assessment insulin resistance (HOMA-IR) score, which is a measure of insulin resistance, were collected." (PMID 33381605, 2020).
Insulin resistance (continued). "Their binding to insulin, a process known as insulin estrogenization, hinders insulin affinity of binding to insulin receptors, resulting in vivid insulin resistance." (PMID 33333828, 2020). "In Cohort A, Lactobacillus was positively correlated with fasting insulin levels (r = 0.44) and HOMA-IR (r = 0.45), indicating an association of this taxon with insulin resistance (P < 0.05)." (PMID 32956361, 2020). "-Inhibition of miR-122 via inhibition of JNK pathway and restoring the function of IRS1/IRS2 and insulin signaling. -Abrogated the insulin resistance observed in mice under high fat diet." (PMID 33585535, 2020). "For a long time, there have been reports of studies indicating that insulin and insulin resistance give rise to renal dysfunction while, conversely, impairment of kidney function brings about insulin resistance." (PMID 33270683, 2020). "Insulin resistance in skeletal muscle mediated by forkhead box O1 (FOXO1), a critical negative regulator of insulin signaling, has been found to be linked to vitamin D." (PMID 33457118, 2020). "In fact, beta cells respond to chronic nutrient excess and to ensuing insulin resistance by increasing insulin secretion in order to maintain normal levels of glucose." (PMID 32718046, 2020). "While Nrf2 protects cells against oxidative damage and can improve glucose homeostasis and insulin resistance, it can also impair insulin-stimulating ROS signaling." (PMID 32878255, 2020). "In normal subjects, serum levels of insulin after matching were much higher than those before matching because of matching for insulin resistance." (PMID 32429590, 2020). "Elevated glucocorticoid concentration not only leads to insulin resistance, but it has been shown that increased glucocorticoids (GCs) decrease insulin production, secretion and sensitivity." (PMID 33308255, 2020). "Insulin resistance (IR) is a condition characterised by the inability of the peripheral tissues to properly utilize endogenous insulin to maintain glucose homoeostasis." (PMID 33116232, 2020). "Nonetheless, this drug is beneficial to the metabolism of patients with T2DM because of its insulin-independent action that releases excessive energy status or insulin resistance." (PMID 32656265, 2020). "Defining the pathways of insulin resistance and uncovering potential mechanisms to improve insulin sensitivity are key therapeutic areas requiring further investigation." (PMID 33101053, 2020). "Hyperglycaemia induced by STZ leads to progressive insulin resistance of the peripheral tissues, which results in mice being unresponsive to insulin." (PMID 32550230, 2020). "Glo-1 activity is highly correlated with insulin sensitivity, and hyperglycemia and insulin resistance were increased in Glo-1 knockout animals." (PMID 32825285, 2020). "A crucial effect exerted by MI and DCI in PCOS patients is the insulin sensitizing action, which improves insulin resistance, mirrored by the homeostatic model assessment (HOMA-IR) index decrease." (PMID 33260918, 2020). "When pre-pregnancy insulin resistance in obese women superimposes to the pregnancy-related insulin resistance, it leads to an increased insulin response, which affects early placental growth and gene expression." (PMID 33424775, 2020). "Oral hypoglyceamic agents (OHAs) can reduce insulin resistance and facilitate insulin secretion during the early stage of the disease." (PMID 33053901, 2020). "The connection between decreased glucose uptake and reduced insulin secretion, as well as insulin resistance, is confirmed in already published studies." (PMID 32947606, 2020). "DAG is known for its ability to exacerbate hepatic insulin resistance by interfering with insulin signaling via PKC activation." (PMID 33343375, 2020). "Insulin resistance is defined as the reduction in insulin’s ability to stimulate glucose uptake by the body’s peripheral tissues." (PMID 32899870, 2020).
Insulin resistance (continued). "The group of DM mice exhibited a significant reduction in serum insulin levels at the 36th week, possibly due to long-term insulin resistance, which can undermine the secretory function of islet β cells." (PMID 32194828, 2020). "Increased adiposity, decreased compensatory insulin response, or genetic variation related to insulin resistance have been proposed as possible mechanisms." (PMID 32993664, 2020). "The increased levels of C-peptide are also correlated with excessive secretion of insulin, secondary to insulin resistance." (PMID 31963760, 2020). "This framework was specifically developed to elucidate the link between in vitro insulin signaling and in vivo glucose homeostasis, which is of interest in the study of insulin resistance." (PMID 33324238, 2020). "Mice in the HFD group exhibited higher levels of fasting blood glucose and serum insulin, as well as higher values of insulin resistance index (HOMA-IR) and quantitative insulin sensitivity check index (QUICKI) than those in the control group (p < 0.01)." (PMID 32971772, 2020). "Offspring from diabetic rats exhibit increased glucose, insulin, and triglyceride levels due to glucose intolerance and insulin resistance, which are markers of T2DM." (PMID 32977673, 2020). "While insulin resistance in cows can increase fetal glucose availability, it can impair maternal-fetal nutrient transfer, as insulin stimulates synthesis of muscle proteins, and inhibits their degradation." (PMID 32854111, 2020). "SRT1720 treatment improved insulin sensitivity of liver, skeletal muscle and adipose tissue in insulin resistance Zucker fa/fa rats." (PMID 32796716, 2020). "In contrast, SQE supplementation decreased serum insulin and glucose levels, and improved body insulin resistance in the rats of the HF group." (PMID 33297496, 2020). "T2DM is described by insulin resistance mainly due to modified insulin production however with a certain capacity for insulin production without destroying autoimmune β-cell." (PMID 32544194, 2020). "Oxidative stress upregulated miR-200a, which directly targets the 3'UTR of Insr and Irs1, leading to hindered insulin signaling and impaired insulin-dependent glucose uptake in skeletal muscle, ultimately promoting the development of insulin resistance." (PMID 32802189, 2020). "In our experiment, the HOMA-IR level in the NAFLD group was significantly higher than that in the control group, indicating that insulin resistance in the NAFLD group led to a decrease in insulin sensitivity." (PMID 32963741, 2020). "Remarkably, the chromosome 3 was already reported to be exhibiting the strongest linkage to the serum insulin concentrations and fasting insulin resistance index." (PMID 32751097, 2020). "Another study on individuals with normal glucose tolerance who were hyperinsulinemic and had the metabolic syndrome reveals that metformin reduces insulin resistance and restores physiological insulin secretion." (PMID 33321755, 2020). "We also evaluated the lipid profile, insulin and glucose levels, homeostatic model assessment of insulin resistance (HOMA-IR), and C-reactive protein (CRP) levels." (PMID 31973121, 2020). "After adjusted for age, sex, and preoperative DM status, FGF21 became significantly and positively related to C-peptide (β = 18.887), insulin (β = 2.399), and homeostasis model assessment of insulin resistance index (β = 8.566) after surgery." (PMID 32210348, 2020). "In this context, the hypothetical recruitment of participants with overweight or obesity would have expanded the variability in terms of insulin sensitivity indexes, given the well-known relation between adiposity and insulin resistance." (PMID 32933059, 2020). "Insulin resistance is a state in which peripheral tissue demonstrates impaired glucose uptake in response to insulin, which is an early predictor of Type 2 diabetes and is highly correlated with obesity." (PMID 32911464, 2020).
Insulin resistance (continued). "The associations of genetically predicted IGF-1 levels with type 2 diabetes and coronary artery disease were similar after adjustment for insulin levels or insulin resistance, whereas adjustment for height resulted in somewhat stronger associations." (PMID 32548700, 2020). "Consistent with previous studies, the present study revealed that the high-fructose diet induced insulin resistance, as indicated by high levels of serum insulin and glucose, and high values of HOMA-IR." (PMID 33297496, 2020). "Insulin resistance in cancer patients is demonstrated by decreased insulin sensitivity or impaired glucose tolerance and is suspected to increase during cachexia progression." (PMID 32850383, 2020). "The homeostasis model assessment (HOMA)—insulin resistance (IR) index was also increased in Lgals3−/− versus wild type mice and the euglycemic-hyperinsulinemic clamp confirmed the lower whole-body insulin sensitivity in the Lgals3−/− animals." (PMID 33208796, 2020). "Both fasting insulin levels and insulin resistance index (HOMA-IR) were increased in MHF offspring (p < 0.05 and p < 0.01 respectively)." (PMID 33027895, 2020). "To explore the mechanism(s) by which deletion of muscle LRP2 contributes to systemic insulin resistance, we measured the ability of insulin to activate insulin signaling in insulin-sensitive tissues of M-LRP2−/− mice." (PMID 32332780, 2020). "PHLPP1 expression is enhanced in the skeletal muscle of insulin resistant rodents that also exhibit ER stress, an important mediator of insulin resistance." (PMID 32872540, 2020). "In summary, we have characterized a patient with a rare insulin resistance and overgrowth syndrome (insulin-mediated pseudoacromegaly)." (PMID 33210059, 2020). "As obesity is closely correlated with insulin resistance and glucose tolerance, fasting blood glucose and fasting serum insulin was measured, and HOMA-IR was calculated according to the established formula." (PMID 32256675, 2020). "Several surrogate indices using glucose and insulin levels have been devised as alternative measures of insulin sensitivity, including the homeostasis model assessment of insulin resistance (HOMA‐IR) and Matsuda index." (PMID 32484250, 2020). "Changes in the activity of key signal molecules in the insulin signal pathway will affect the transmission of insulin signal, and then affect the biological activity of insulin, thus affecting the occurrence of insulin resistance and T2DM." (PMID 32964053, 2020). "More importantly, the IRS2/AKT pathway was critical for liver insulin signaling to regulate insulin resistance in muscle and liver of diabetic rats." (PMID 32169080, 2020). "In the MHW group, insulin, homeostatic model assessment of insulin resistance (HOMA-IR), γ-glutamyltransferase (GGT), high-sensitivity C-reactive protein (hs-CRP), and interferon (IFN)-γ showed significant increases compared to those in the other groups." (PMID 32346379, 2020). "Similar to type 2 diabetic patients, people with opium use disorder show insulin resistance and an increase in the insulin level of the blood." (PMID 32303254, 2020). "Obese patients showed significantly higher BMI- standard deviation score (SDS) weight-SDS, waist circumference, levels of insulin and Homeostatic model assessment for insulin resistance (HOMA-IR) than controls (p < 0.001)." (PMID 32635185, 2020). "Permanently elevated insulin concentrations in the blood are often considered as an attempt to overcome insulin resistance." (PMID 32819363, 2020). "Next, the ITT results suggest that male WT animals that were fed a HD developed insulin resistance, whereas all other groups remained sensitive to insulin." (PMID 32079362, 2020). "At the same time, by increasing insulin sensitivity in patients, further lowering blood sugar and improving insulin resistance, and achieving the effect of treating PCOS." (PMID 32785222, 2020).